CDKN2A (cyclin dependent kinase inhibitor 2A)
Diseases named in the same sentence as CDKN2A in open-access papers (continued):
Sharing a sentence is not in itself a finding about the gene and the disease.
tumor (continued). "It has been postulated that CTCF acts as a tumor suppressive factor, since its function has been associated with altered expression of tumor-suppressor gene, such as E-cadherin, retinoblastostoma, RASSF1A or p16/CDKN2A." (PMID 25352953, 2014). "The known tumor suppressors CDKN2A and PTEN provide criteria of recurrent focal DNA gains or losses that correlate well with transcript expression." (PMID 24670534, 2014). "In our study, gene hypermethylation was detected most commonly in CDH1 and CDKN2A genes in central and peripheral parts of the tumor." (PMID 24782031, 2014). "They reported a homozygous G to C trans-version in Exon 3 of CDKN2A in 78.7% of cases, which correlated with higher tumour grade." (PMID 24877109, 2014). "Comparing the DNA copy number for CDKN2A, a known tumor suppressor to its mRNA expression reveals the robust manner in which this molecular alteration is associated with the genes expression, and its frequent inactivation in the NCI-60." (PMID 24670534, 2014). "Among the tumor suppressors, both the CDKN2A (p16) and PTEN losses are consistent with prior reports of deletion in cancers." (PMID 24670534, 2014). "In particular, EBNA3A and EBNA3C cooperate to repress the expression of the pro-apoptotic tumor-suppressor gene BCL2L11 (BIM) and the cyclin-dependent kinase inhibitor gene CDKN2A encoding p16INK4a." (PMID 25092922, 2014). "In univariable analysis, tumor stage (log rank P = 0.006) and grade (P < 0.001), HPV DNA (P < 0.004), Chromosome 9 (P = 0.04) and the A148T polymorphism (rs 3731249) in CDKN2A (P = 0.02) were associated with progression following treatment." (PMID 25142434, 2014). "Our study has provided the first glimpse of the genetic underpinnings of AciCC, highlighting changes in the tumor suppressors CDKN2A and PPP1R13B." (PMID 23653877, 2013). "Since p16/CDKN2A is frequently inactivated genetically or epigenetically in cancer cells, the p16/CDKN2A locus is suspected to be a major tumor suppressor gene." (PMID 23776618, 2013). "As for genomic loss, 9p21.3 (CDKN2A), 9p23-p24.1 (PTPRD) and 13q14.2 (RB1) were significantly less frequently deleted in ALK fusion-positive tumours." (PMID 23289484, 2013). "CDKN2A acts as a tumour suppressor and maintains cells in a state of growth arrest, both in replicative and stress induced-senescence." (PMID 23994067, 2013). "MTAP (DriverNet rank 3) and known tumor-suppressor CDKN2A (DriverNet rank 4) are known to be co-deleted and they were observed as such in our analysis." (PMID 23383675, 2012). "CDKN2A encodes for p16 which is a cyclin-dependent kinase inhibitor (CDKI) and a critical component of the pRB/p16 tumor suppressor axis." (PMID 22292443, 2012).
tumor (continued). "In this study, we demonstrated that factors associated with poor outcomes in stage I and II nonsquamous NSCLC included nonadenocarcinoma, positive expression of p16INK4 and RB1 by IHC, and with CNV of CDKN2A gene in the tumor cells." (PMID 22619677, 2012). "TAGCNA identifies SCEs that are known to be involved with proto-oncogenes (e.g. EGFR, CDK4) and tumor suppressor genes (e.g. CDKN2A, CDKN2B), and provides many additional SCEs with potential biological relevance in these data." (PMID 22815924, 2012). "ANRIL directly binds to the SUZ12 protein, an essential component of polycomb repressive complex 2, and is required for SUZ12 occupancy of the CDKN2A/CDKN2B tumour suppressor genes as well as for their epigenetic silencing." (PMID 23101500, 2012). "The CCND1/CDKN2A ratios of all the normal tissues were significantly higher compared with those of corresponding tumor tissues, indicating that the RB1 status of all the normal tissues was positive." (PMID 21447152, 2011). "CDKN2A/ARF is among the most commonly mutated loci in human cancer, encoding two different tumor suppressors translated from alternatively spliced mRNAs." (PMID 21526190, 2011). "Using the cervix uteri as a model, we have shown that smoking increases the risk of acquiring methylated forms of CDKN2A, a TSG, the epigenetic inactivation of which is strongly associated with the pathogenesis of neoplasia at many sites." (PMID 21487403, 2011). "BRAF-wild-type clones present in primary tumours and metastases are likely to contain mutations or copy number alterations affecting genes other than BRAF, such as NRAS, KIT, cyclin D1, PTEN and CDKN2A." (PMID 21224857, 2011). "The molecular function of CDKN2A in tumor cells is a subject of considerable investigation, and it is still not clear." (PMID 21843312, 2011). "For methylation as a mechanism of sarcomagenesis, two prominent tumor suppressor loci, CDKN2A and RASSF1A, as well as one important apoptosis activator, caspase 8, have been implicated." (PMID 21437220, 2011). "The functional consequences of CDKN2A exon 2 DNA methylation in tumor samples merits further investigation." (PMID 21731750, 2011). "Transplantation of gammaretroviral transduced hematopoietic cells in mice with knocked-out Cdkn2a tumor suppressor gene leads to accelerated tumor growth in case a cellular proto-oncogene is virally activated." (PMID 21994741, 2011). "Two of the cases used for this analysis showed log2 tumor DNA:reference DNA ratios < -1.0 at the CDKN2A/B locus, highly suggestive of an homozygous deletion." (PMID 21615919, 2011). "No CDKN2A mutations were identified in G500 heterozygotes as evident by dHPLC and sequence analysis of all CDKN2A exons and exon/intron boundaries in amplicons of tumor and blood leukocyte extracted DNA." (PMID 22046342, 2011). "This CDKN2A gene turned out to be an important cell cycle regulator with a key tumour suppressor role acting in the gestation or promotion of several cancer types." (PMID 24281082, 2010). "Using Methylight assay, methylation status of 8 CpG islands of the first exon of CDKN2A was evaluated in 33 HCCs and the corresponding non-tumor liver samples." (PMID 20569442, 2010). "Reduced gene dosage across 9p21.3 was associated with increased tumor thickness, mitotic rate, and ulceration (P = 0.02, 0.02, and 0.002, respectively), specifically in coding regions impacting on CDKN2B and P14ARF and CDKN2A." (PMID 20140953, 2010). "We demonstrated that intracellular-delivered Id1/3-PA7 colocalised to Id1 and Id3 and promoted increased expression of the tumour suppressor CDKN2A in a dose-dependent manner." (PMID 20842131, 2010).
tumor (continued). "While causal variants within 9p21.3 have yet to be identified, the risk associated SNPs cluster together within a 53 kb region roughly 100 kb centromeric to the INK4/ARF (CDKN2a/b) tumor suppressor locus." (PMID 21151960, 2010). "CDKN2A (also known as p16-INK4A) is a tumor suppressor that binds to the complex of cyclin D1 and cyclin-dependent kinase 4 to repress its ability to phosphorylate the retinoblastoma protein, and consequently, blocks cell cycle progression from G1 to S." (PMID 20465802, 2010). "Only a handful of studies to date have evaluated CDKN2A methylation in the context of tumor budding." (PMID 21317460, 2010). "The inactivation of the CDKN2A gene, which encodes an inhibitor of CDK4 and CDK6, is one of the most common molecular events in human neoplasms." (PMID 22933911, 2010). "CDKN2A is regarded as tumour suppressor gene because it is frequently silenced by deletion or inactivating mutation in human cancers." (PMID 20569442, 2010). "To further characterise differences in the transcriptional response in the two tumour groups, we isolated genes transcriptionally controlled by CDKN2A (p16)." (PMID 18349847, 2008). "Four NB tumors had deletions in the CDKN2A gene region in 9p and one tumor had a deletion on 3p involving the RBMS3 gene." (PMID 18664255, 2008). "Regarding tumour cell proliferation, ID-1 inhibited the promoter region of the tumour suppressor gene CDKN2A/p16, supporting the role of ID-1 as a potential oncogene." (PMID 19002177, 2008). "Alterations of CDKN2A are reported frequently in various human malignancies, but mechanisms of CDKN2A inactivation appear to vary between tumour types." (PMID 17576439, 2006). "The involvement of epigenetic modifications such as promoter methylation is well known for a variety of established tumour suppressor genes, the most prominent examples being the retinoblastoma gene product and the cyclin-dependent kinase inhibitor CDKN2A." (PMID 16404424, 2006). "Statistical analysis of LOH in MLH1, CDKN2A and RB1 genes and clinicohistopathological features of the disease disclosed that LOH in MLH1 and CDKN2A correlates only with tumour grading." (PMID 15083191, 2004). "A second region with frequent LOH occurred in 9/29 (31%) tumours and was centromeric to the CDKN2A locus (D9S1748)." (PMID 15305192, 2004). "Approximately 70% of tumours in our series displaying 9p21–23 LOH had a SRO at a region telomeric to the CDKN2A and MTAP genes, near the IFNA and IFNB genes cluster." (PMID 15305192, 2004). "Our results also suggest that CDKN2A gene deletions are rare events in NB tumours, in agreement with several prior studies in NB." (PMID 15305192, 2004). "Three tumours (one of each malignancy grade studied) were found to have partially methylated the 5' CpG island of CDKN2A." (PMID 9000591, 1997). "Specifically, 9p21 deletions are thought to contribute to melanocytic transformation and tumor initiation, while rearrangements at the CDKN2A locus and p16 inactivation may play a key role in tumor progression." (PMID 41596618, 2026).
tumor (continued). "Although previous studies have shown that tumor tissue-based STK11, KEAP1, and CDKN2A/B mutations are adverse prognostic factors, we further confirm that ctDNA-based STK11, KEAP1, and CDKN2A can predict unfavorable outcomes in patients with non-metastatic NSCLC." (PMID 41491583, 2026). "Furtheranalysis enrolling other molecular entities (e.g., tumor-associatedmRNAs, miRNAs, proteins), relevant tumor-derived mutations (e.g.,EGFRviii; copy number variations in PTEN and CDKN2A/B genes) and different EV isolations methodologies,is encouraged to reach clinical translation." (PMID 40056466, 2025). "Somatic mutations enriched in the low-risk group (e.g., CDKN2A, MUC16, DNAH8) may reflect increased neoantigen load, enhancing tumor visibility to the immune system." (PMID 40909289, 2025). "Similarly, BCL628and BCL929 facilitate tumor progression and are potential therapeutic targets, and CDKN2A promoter methylation correlates with poorer progression-free survival, supporting its prognostic significance." (PMID 41419500, 2025). "For somatic copy number alterations, cases with high PLK3 expression not only demonstrated significant amplification peaks for PIK3C2B, PDGFRA, EGFR, and CDK4, which are defined as oncogenic drivers, but they also showed deletion peaks for tumor-suppressor genes, such as CDKN2A and CDKN2C." (PMID 39866232, 2025). "A study confirming the occurrence of LOH most frequent on chromosome 9 found four patients with biallelic deletion 9p21.3 (three of them had LOH) of the tumor suppressor gene cluster (CDKN2A, CDKN2BAS1, CDKN2B, and DMRTA1), which is fully consistent with our research." (PMID 40805197, 2025). "Both homozygous and hemizygous losses of CDKN2A/B, as well as focal gene amplifications, are linked to poorer overall survival, independent of tumor grade." (PMID 40949165, 2025). "It is tempting to speculate that the tumor-preventive role of early CDKN2A LoF could be further developed as a marker of favorable prognosis in nondysplastic BE." (PMID 39753721, 2025). "Molecular markers now incorporated into the WHO CNS5 classification include TERT promoter mutations and CDKN2A/B deletions, which are sufficient to upgrade a tumor to WHO grade lll even in the absence of high-grade histologic features." (PMID 41552249, 2025). "Butyrate and other short-chain fatty acids (SCFAs) act as endogenous class I/IIa HDACi; their depletion removes a physiological brake on HDAC activity, thereby favoring re-establishment of repressive chromatin and promoter hypermethylation at tumor-suppressor loci (e.g., CDKN2A) in aging urothelium." (PMID 40918525, 2025). "In addition, CDKN2A promoter methylation is a common epigenetic event and an important factor leading to cell proliferation and uncontrolled tumor progression." (PMID 40065477, 2025). "When CDKN2A is highly expressed, it inhibits the proliferation of tumor cells." (PMID 39925808, 2025). "Moreover, CDKN2A can also function as a tumor suppressor in multiple cancer types, such as melanoma, renal cancer, and pancreatic carcinoma." (PMID 41357671, 2025). "These proteins inhibit cell cycle progression; therefore, CDKN2A/B HD may disrupt the regulatory mechanisms controlling tumor cell proliferation, potentially leading to increased protein synthesis and MET accumulation." (PMID 40786409, 2025).
tumor (continued). "Among 39 cases, 27 (69.23%) exhibited a homozygous deletion of the CDKN2A gene in more than 20% of tumour cells, 8 (20.51%) harboured a percentage of heterozygous deletion in over 50% of tumour cells, and 4 (10.26%) had no detectable CDKN2A copy number variation." (PMID 40566743, 2025). "There appears to be less consistency in the observation of changes in the CDKN2A and SMAD4 tumour suppressor genes, with estimates for their functional loss ranging from 15% to 60%, perhaps contributed by different assessment technologies and differences between the analysed populations." (PMID 40723241, 2025). "Similarly, in CDKN2A gene amplifications, the richest tumor vascularization is observed, followed by gene deletions and normal status (p = 0.008)." (PMID 40002588, 2025). "Mutations in CDKN2A and CDKN2B can lead to uncontrolled cell proliferation and even tumor growth." (PMID 40535548, 2025). "When analyzing all tumors, higher T reg cell activity and increased expression of CDKN2A were associated with non-responsiveness within an individual patient, consistent with the known function of T reg cells in suppressing anti-tumor immune responses." (PMID 39885167, 2025). "CDKN2A gene alterations are increasingly recognized for their role in tumor biology and prognosis." (PMID 40227557, 2025). "CDKN2A encodes two proteins, p16(INK) and p14(ARF), both of which are tumor suppressors." (PMID 39932614, 2025). "Furthermore, in vitro assay also showed that the four risk genes (HSPA1A, SEMA4C, CDKN2A, ARHGAP4) were overexpressed in the tumor cells." (PMID 39950044, 2025). "However, both primary material and PDO from patient 4 contained a mutation in CDKN2A, another well-known driver mutation of PDAC, confirming the PDAC origin of this tumor material." (PMID 41141365, 2025). "Extensive genomic analyses have revealed frequent inactivation of key tumor suppressors, such as neurofibromin 2 (NF2), BRCA1-associated protein 1 (BAP1), and cyclin-dependent kinase inhibitor 2A (CDKN2A), through various mechanisms, thereby providing new targets for treatment." (PMID 40362535, 2025). "Tumor behavior linked to NF2, CDKN2A/B deletions, and TERT mutations may influence radiotherapy response." (PMID 39779595, 2025). "Notably, silencing of CDKN2A inhibited the activity of migration and invasion and promoted apoptosis of tumor cells." (PMID 39950044, 2025). "Since this is a prospective study based on PGOs for which tumor diagnostics were not available a priori, CDKN2A/B loss and 1p/19q co-deletion groups were non-balanced." (PMID 39578301, 2025).